ZBTB43 (zinc finger and BTB domain containing 43)
Description:
May be involved in transcriptional regulation.
Synonyms: KIAA0414; ZBTB22B; ZNF297B; ZNF-X; FLJ22470
Tractability: PROTAC: UniProt records ubiquitination sites on it; ubiquitination databases record sites on it.
Target class: Transcription factor
Gene: Protein-coding gene on chromosome 9 (126,804,988 to 126,838,210, forward strand). Ensembl gene ENSG00000169155.
Subcellular location: Nucleus
Subcellular location (Human Protein Atlas): Nucleoli; Nucleoplasm
Gene Ontology:
Molecular function: protein binding; RNA polymerase III general transcription initiation factor binding; sequence-specific double-stranded DNA binding; DNA-binding transcription factor activity, RNA polymerase II-specific; RNA polymerase II cis-regulatory region sequence-specific DNA binding
Biological process: regulation of transcription by RNA polymerase II
Cellular component: chromatin; nucleus
Genetic constraint (gnomAD): Loss-of-function variants: 1 observed, 5.94 expected, observed/expected ratio (o/e) 0.17, 90% interval 0.059 to 0.8. That is too few expected variants to judge how well the gene tolerates losing a copy. Missense variants: 48 observed, 131.36 expected, observed/expected ratio (o/e) 0.37, 90% interval 0.29 to 0.47. Synonymous variants: 46 observed, 45.14 expected, observed/expected ratio (o/e) 1.02, 90% interval 0.8 to 1.3.
Homologues: Orthologues: chimpanzee ZBTB43 (100% identical), macaque ZBTB43 (99% identical), dog ZBTB43 (99% identical), pig ZBTB43 (99% identical), rabbit ZBTB43 (98% identical), guinea pig ZBTB43 (98% identical), mouse Zbtb43 (93% identical), rat Zbtb43 (92% identical), tropical clawed frog zbtb43 (75% identical), zebrafish zbtb43 (47% identical), Drosophila melanogaster klu (13% identical), Caenorhabditis elegans klu-2 (10% identical), and 1 more. Paralogues in human: ZBTB5 (22% identical), ZBTB7A (22% identical), ZNF367 (10% identical), ZNF740 (7% identical).
Diseases named in the same sentence as ZBTB43 in open-access papers:
ZBTB43 is named in the same sentence as 8 diseases in open-access papers, as found by Europe PMC text mining. Sharing a sentence is not in itself a finding about the gene and the disease. The quoted sentences say what the papers report.
tumour (1 paper, 2024). "We report ZBTB43::NTRK2 as a new fusion that has not been previously reported in any tumour." (PMID 39014476, 2024).
ZBTB43 also shares sentences with these, for which no sentence is quoted: blood disease (1 paper); cancer (1); Diamond-Blackfan Anemia 4 (1); familial hyperlipidemia (1); hemochromatosis type 2 (1); high blood pressure (1); Marfan syndrome (1).